C9orf72 (C9orf72-SMCR8 complex subunit)
Diseases named in the same sentence as C9orf72 in open-access papers (continued):
Sharing a sentence is not in itself a finding about the gene and the disease.
neurological diseases (24 papers, 2016 to 2025). "The proteinous nanopore, however, can be blocked by arginine-containing polydipeptide repeats (DPRs) of proteins resulting from the disordered C9orf72 gene as a potential cause of serious neurological diseases." (PMID 39246336, 2024). "The 8×Arg-His repeats are reminiscent of dipeptide repeat expansions in the human C9ORF72 gene, which cause neurological disease in humans." (PMID 36369503, 2022). "Our study presented here analyses the available data for C9orf72 at the gene level and provides some insights into the regulation of C9orf72 and its close linkage to other genes implicated in nervous system disorders." (PMID 29479499, 2018). "The non-exclusive pathogenic mechanisms by which C9orf72 repeat expansions contribute to these neurological disorders include loss of C9orf72 function and gain-of-function determined by toxic RNA molecules and dipeptides repeats protein toxicity." (PMID 29326544, 2017). "Several mechanisms have been proposed to explain how C9orf72 expansion causes neurological disease." (PMID 32116499, 2020). "Only three of our seven probands (43%) had a family history of neurological disease, which is significantly less than for C9orf72 and SOD1 mutations and suggests that TIA1 mutations may be variably penetrant." (PMID 29216908, 2017). "To examine whether C9ORF72 haploinsufficiency induces neurological disease, we created a C9orf72-deficient mouse line." (PMID 26979938, 2016). "Consistent with a role for dRIFs in neurological disease, cells expressing the G4C2 repeat in the C9orf72 gene that can cause ALS show activation of PKR and concentration of PKR into discreet cytoplasmic foci that we suggest are dRIFs." (PMID 35939694, 2022). "Many genes play an important role, with TARDBP, SQSTM1, VCP, FUS, TBK1, CHCHD10, and most importantly, C9orf72 being critical genetic players in these neurological disorders." (PMID 33805659, 2021). "TARDBP, SQSTM1, VCP, FUS, TBK1, CHCHD10, and most importantly C9orf72, are the critical genetic players in these neurological disorders." (PMID 32116499, 2020). "It is noteworthy that the inhibition of SPT4 in human cells and model organisms has been proposed as a strategy to reduce aberrant transcription across repeat expansions in certain neurological diseases, including the case of R-loop-prone C9orf72 gene expanded in ALS." (PMID 39120648, 2024). "They account for more than 40 neurological disorders, including HD (CAG repeat expansion in HTT), FXTAS and FXS (CGG repeat expansion in FMR1), dentatorubral‐pallidoluysian atrophy (DRPLA; OMIM# 125370; CAG in ATN1), C9orf72‐related disorders (GGGGCC in C9orf72) and some SCA." (PMID 33816657, 2021).
movement disorder (9 papers, 2014 to 2025). Neurological conditions resulting in abnormal voluntary or involuntary movement, which may impact the speed, fluency, quality and ease of movement. "We aimed to determine the frequency and phenomenology of movement disorders (MD) in carriers of HRE in C9orf72 through a retrospective review of patients' medical records." (PMID 33977144, 2021). "In our highly selected population (cases of MAPT, PGRN and C9orf72 causing FTLD and a movement disorder), the most common gene involved was MAPT with a prevalence of 44% followed by PGRN (32%) and C9orf72 (24%)." (PMID 27100392, 2016). "In conclusion, our results do not suggest that an expanded repeat number in the C9orf72 gene plays a major role in the susceptibility to the wider spectrum of movement disorders." (PMID 24803912, 2014). "A short peptide termed Myr‐C9orf72 was used to verify whether interfering with Cdk5 phosphorylation at the Ser9 site of the C9orf72 protein could alleviate autophagy disorder, neuronal death, and movement disorder in PD models." (PMID 37353944, 2023). "The operational criteria for phenoconversion to a movement disorder phenotype are not yet well established, perhaps in part due to the rarity of an extrapyramidal syndrome as the first fully manifest phenotype among C9orf72 repeat expansion carriers." (PMID 40794569, 2025). "Herein, we demonstrate that the C9orf72 repeat expansion is not a common cause of disease for sporadic AD, FTD, PD, and other related movement disorders in our population." (PMID 24803912, 2014). "Of note, all PSP-RS patients had eye movement dysfunction defined by the Movement Disorder Society’s criteria for PSP (i.e., vertical supranuclear gaze palsy and slow velocity of vertical saccades), but only 2 of 5 FTLD-TDP-PSP patients had this sign, one of whom had a C9ORF72 repeat expansion." (PMID 40635087, 2025). "Importantly, experts from other fields (e.g. movement disorders) should also be engaged, since C9orf72 disease is not limited to ALS and FTD phenotypes." (PMID 40794569, 2025).
psychiatric diseases (9 papers, 2017 to 2025). "Importantly, among the referred psychiatric disorders associated to c9orf72 expansion, obsessive-compulsive disorder seems to be excluded, though rigid stereotyped behavior with obsessiveness is frequently observed in carriers." (PMID 30914912, 2019). "In addition to ALS and FTD, the C9orf72 gene expansion mutation has been linked with other neurodegenerative and psychiatric disorders, although etiological roles remain unknown." (PMID 32678027, 2020). "C9orf72 carriers may initially present with neuropsychiatric symptoms that appear to be a psychiatric disorder but are actually psychiatric symptoms in the context of a neurodegenerative disorder." (PMID 37548032, 2024). "In order to investigate phFTD without the interference of an alternative diagnosis we ruled out alternative psychiatric disorders, neuropsychological progression and presence of the C9orf72 mutation." (PMID 27436017, 2017). "A family history of psychiatric diseases was significantly more frequent in C9ALS patients, supporting the role of C9ORF72 in psychiatric disease development." (PMID 40149460, 2025). "Notwithstanding the major role of c9orf72, a non-trivial residual association between ALS and psychiatric disorders persists even after excluding repeat expansion carriers from genetic analyses." (PMID 30914912, 2019).
cancer (8 papers, 2018 to 2024). A tumor composed of atypical neoplastic, often pleomorphic cells that invade other tissues. "As a proof of concept, we targeted loci in healthy donor DNA, including a highly variable hexanucleotide repeat in C9orf72, and four cancer-related genes with guide RNAs previously validated for PCR-free targeted sequencing (GSTP1, KRT19, GPX1, SLC12A4)." (PMID 33830997, 2021). "For instance, we use it to identify novel cancer-related genes, i.e. PRDM11, C9orf72, MINDY3, and H4C6, that could have an important role in the studied cancer types." (PMID 37084262, 2023). "The ATM deficiency in C9orf72-ALS patients, however, does not appear to predispose to cancer." (PMID 29584802, 2018). "Thus, one possible explanation for the absence of cancer in C9orf72-ALS is the retention of functional homologous recombination and ATM-mediated cell cycle checkpoint, akin to RIDDLE." (PMID 29584802, 2018).
tumours (6 papers, 2016 to 2022). "Preclinical studies showed how the C9orf72 knockout, the most common cause of ALS, caused the proliferation of unexpected tumours in different mouse tissues." (PMID 35620002, 2022). "It has been suggested that C9orf72 is a member of a superfamily called differentially expressed in normal and neoplasia (DENN), which contains GDP/GTP exchange factors (GEFs) that activate regulators of membrane trafficking known as Rab-GTPases." (PMID 31594549, 2019). "The enlargement of C9orf72−/− spleens and LN suggests a disease process such as neoplasm or immune dysregulation, an unexpected finding given that ALS/FTD is not linked to such pathology in human patients." (PMID 26979938, 2016). "Furthermore, a 2016 preclinical study showed how the C9orf72 knockout, the most common cause of ALS, caused an unexpected increase in tumours in mice." (PMID 35620002, 2022). "Likewise, the following marker genes were selected for analysis in PF tumours: LAMA2, ALDH1L1, SLC6A13, IGSF1, and CXorf67 for PFA; and NELL2, DNAH1, CEP83, C9orf72, and NXNL2 for PFB tumours." (PMID 34314101, 2021).
immune dysfunction (5 papers, 2018 to 2023). "The exact underlying mechanism of this immune dysfunction is still unclear but might be related to the high expression level of C9orf72 in myeloid cells." (PMID 32876811, 2020). "Similarly, mice lacking C9orf72 in all tissues exhibit decreased body weight and immune dysfunction without motor neuron impairments or degeneration." (PMID 32876811, 2020).
infection (5 papers, 2018 to 2022). The state of being infected such as from the introduction of a foreign agent such as serum, vaccine, antigenic substance or organism. "We hypothesized that this effect may also reflect in host immune response to infections and that harboring C9orf72 HREs of intermediate length may then modulate this response." (PMID 34209673, 2021). "To further examine the effect of gRNA1-2 on C9ORF72 protein expression, we established three independent HEK293 cell lines derived from a single edited cell by gRNA1-2 infection." (PMID 35383205, 2022). "Given the role of C9orf72 in TLR and type I IFN pathways, it is tempting to speculate that intermediate repeats, likely through gene expression modulation, may influence host response to infection with SARS-CoV-2 and perhaps further viruses." (PMID 34209673, 2021). "The contribution of these lncRNAs to cell–trait pairs is also supported by their dynamic upregulation during iPSC (induced pluripotent stem cells) differentiation to neurons (APP and MAPT antisense) or in immune cells upon infection (C9orf72 and LRRK2 antisense) (data not shown)." (PMID 30610612, 2019).
genetic disorders (3 papers, 2019 to 2022). "The massive sequencing approach based on NGS platforms has become the first tier for molecular diagnosis of heterogeneous genetic disorders such as AD and FTD, integrated with PCR analyses of the C9orf72 hexanucleotide repeat expansion and the PRNP octapeptide repeat region." (PMID 33203472, 2020).
neuromuscular disease (3 papers, 2023 to 2025). "For instance, under stress stimuli, circ-C9ORF72 was exported from the nucleus into the cytoplasm, the nuclear export of circ-C9ORF72 accounted for neurological or neuromuscular diseases via yielding dipeptide repeat proteins." (PMID 38087322, 2023). "To clarify the genetic etiology of this HSP pedigree, we first performed fragment analysis of neuromuscular disease in the proband and found no dynamic variants (such as SCAs and C9orf72)." (PMID 40225166, 2023). "However, patients and asymptomatic individuals with a medical history or concomitant presence of neuromuscular diseases in the examined arm were carefully excluded, thus minimizing other pathophysiological confounders beyond ALS or C9orf72 carriership." (PMID 40923569, 2025).
infectious disease (2 papers, 2016 to 2022). A disorder directly resulting from the presence and activity of a microbial, viral, or parasitic agent in humans. "A NextBio enrichment analysis of this sample set revealed the strongest perturbations in gene sets involved in immune response, mouse models of inflammatory conditions, and human infectious diseases, consistent with C9orf72 ablation resulting in global immune dysregulation." (PMID 26979938, 2016).
neurogenetic disease (2 papers, 2023 to 2024). "Among the four, PSEN1 and PSEN2 are known AD-related genes, reported in AlzGene, while C9orf72 and SOD1 are known to be relevant to neurogenetic disease and possess AD-relevant literature support in GeneCards." (PMID 38627848, 2024).
brain disease (1 paper, 2019). "This included brain disease traits with expression in the nervous system (antisense to APP and two antisense lncRNAs to MAPT) as well as immune-related diseases and enrichment in immune cells (antisense to LRRK2 and C9orf72)." (PMID 30610612, 2019).
genetic mitochondrial disorders (1 paper, 2023). "The genetic syndromes reported in the literature are 22q11 deletion syndrome, Prader–Willi syndrome, C9orf72 mutations, Fragile X premutation disorders, BSC1L mutation, 3q29 recurrent deletion, 15q duplication syndrome, and genetic mitochondrial disorders." (PMID 37761400, 2023).
C9orf72 also shares sentences with these, for which no sentence is quoted: Ataxia (6 papers); Fuchs endothelial corneal dystrophy (6); corticobasal degeneration (5); spinocerebellar ataxia type 8 (4); Stroke (4); muscular dystrophy (3); neurodevelopmental disorder (3); Pick disease (3); rheumatoid arthritis (3); spinal muscular atrophy (3); benign adult familial myoclonic epilepsy (2); Cerebellar Ataxia (2); cognitive disorder (2); colon carcinoma (2); glioma (2); Huntington disease-like 2 (2); mood disorder (2); myotonic dystrophy (2); Neurodegeneration (2); oculopharyngeal muscular dystrophy (2); spinocerebellar ataxia type 1 (2); Spinocerebellar ataxia type 3 (2); Aicardi-Goutieres syndrome (1); alkaptonuria (1); Apathy (1); asthma (1); autosomal dominant disease (1); beta thalassaemia (1); bladder cancer (1); brain injuries (1).
A further 50 diseases each share a sentence with C9orf72 in 1 paper.